CDYL2 (chromodomain Y like 2)
Synonyms: FLJ38866; PCCP1
Tractability: Small molecule: a structure with a bound ligand is known; a high-quality ligand is known. PROTAC: ubiquitination databases record sites on it; a small molecule that binds it is known.
Target class: Epigenetic regulator; Reader; Methyl-lysine/arginine binding protein; Chromodomain
Gene: Protein-coding gene on chromosome 16 (80,597,907 to 80,804,598, reverse strand). Ensembl gene ENSG00000166446.
Subcellular location: Nucleus
Gene Ontology:
Molecular function: protein binding; transcription corepressor activity; histone H3K27me3 reader activity; histone H3K9me2/3 reader activity
Biological process: chromatin organization; negative regulation of DNA-templated transcription
Cellular component: nucleus
Genetic constraint (gnomAD): Loss-of-function variants: 23 observed, 45.68 expected, observed/expected ratio (o/e) 0.5, 90% interval 0.36 to 0.71. The synonymous counts are far from expectation, so gnomAD's model fits this gene poorly and the ratio says little. Missense variants: 678 observed, 663.24 expected, observed/expected ratio (o/e) 1.02, 90% interval 0.96 to 1.09. Synonymous variants: 360 observed, 274.8 expected, observed/expected ratio (o/e) 1.31, 90% interval 1.2 to 1.43.
Homologues: Orthologues: chimpanzee CDYL2 (98% identical), macaque CDYL2 (97% identical), pig CDYL2 (94% identical), rabbit CDYL2 (93% identical), mouse Cdyl2 (92% identical), guinea pig CDYL2 (91% identical), rat Cdyl2 (90% identical), tropical clawed frog cdyl2 (80% identical), dog CDYL2 (66% identical), Drosophila melanogaster Dci (13% identical), Caenorhabditis elegans B0272.4 (13% identical), Caenorhabditis elegans ech-5 (13% identical), and 6 more. Paralogues in human: CDYL (52% identical), CDY2A (41% identical), CDY2B (41% identical), CDY1B (41% identical), CDY1 (40% identical), ECHDC2 (16% identical), ECHDC3 (15% identical), ECHS1 (15% identical), AUH (15% identical), ECH1 (13% identical), HIBCH (12% identical), ECHDC1 (11% identical), and 1 more.
Diseases named in the same sentence as CDYL2 in open-access papers:
CDYL2 is named in the same sentence as 12 diseases in open-access papers, as found by Europe PMC text mining. Sharing a sentence is not in itself a finding about the gene and the disease. The quoted sentences say what the papers report.
breast carcinoma (7 papers, 2018 to 2023). "The transcript variants of CDYL2 were found to be differently associated with breast cancer, suggesting a new therapeutic strategy targeting specific CDYL2 isoforms." (PMID 35176995, 2022). "These enhancers activate the expression of the CDYL2 gene suggesting a new association mechanism between rs9940301 and breast cancer through physical interactions with enhancers regulating CDYL2 gene expression." (PMID 35176995, 2022). "Several genetic variants related to CDYL2 have been identified by GWAS to be associated with breast cancer progression and development, including rs13329835 found in the intergenic region of CDYL2 gene." (PMID 35176995, 2022). "The most frequently and highly expressed CDYL2 variants in breast cancer cell lines and primary breast tumors were CDYL2a and CDYL2b." (PMID 32373210, 2020). "In summary, findings presented suggest that CDYL2 transcript variants exert discrete roles in breast cancer growth and metastasis through differentially regulating alternative splicing and transcription events." (PMID 32373210, 2020). "Results showed that high expression of CDYL2 was associated with better relapse-free survival (RFS) of all patients with breast cancer." (PMID 32373210, 2020). "The effect of CDYL2 transcript variants on the malignant phenotypes of breast cancer cells was examined through in vitro and in vivo assays." (PMID 32373210, 2020). "Elevated levels of CDYL2 are associated with poor clinical outcomes in ER+ breast cancer." (PMID 35740522, 2022). "In this study, we provide evidence for the first time that two CDYL2 transcript variants, named CDYL2a and CDYL2b, are predominantly expressed in human breast cancer cell lines and primary breast tumors and exert discrete functions in breast cancer growth and metastasis." (PMID 32373210, 2020). "CDYL2, including an Indel significantly associated with LTN on SSC6, positively regulates breast cancer cell migration, invasion and epithelial-to-mesenchymal transition through p65/NF-κB and STAT3." (PMID 35565484, 2022). "As many of spermatogenesis-related genes are reactivated in human cancer 32, 33, we further examined the expression patterns of CDYL2 in breast cancer." (PMID 32373210, 2020). "To analyze the protein expression levels of different CDYL2 isoforms in human breast cancer cell lines and breast tumors, we conducted immunoblotting analyses using a commercial CDYL2 antibody (#ab183854, Abcam)." (PMID 32373210, 2020). "Moreover, CDYL2 was reported to be overexpressed in breast cancer supporting its role in disease progression." (PMID 35176995, 2022). "Its parental gene CDYL2 is overexpressed and contributes to poor prognosis in breast cancer." (PMID 34485151, 2021). "These bioinformatic analyses data prompted us to further investigate whether CDYL2 is involved in breast cancer development and progression." (PMID 32373210, 2020). "The overexpression of CDYL2 induces EMT and CSC maintenance in MCF7 and MDA-MB-231 breast cancer cells by increasing the Ser536 phosphorylation of p65 and STAT3 activity by Tyr705 phosphorylation, implicating both the NF-kB and STAT3 signaling pathways." (PMID 35740522, 2022). "However, whether CDYL2 is involved in breast cancer progression remains unknown." (PMID 32373210, 2020). "However, whether CDYL2 is involved in breast cancer development and progression remains unknown." (PMID 32373210, 2020). "The nominally significant SNPs included colorectal cancer GWAS SNPs in SMAD7, C11orf93, SCG5, and ATF1, and breast cancer SNPs related to CDKN2B-AS1, FGFR2, GDI2, CDYL2." (PMID 29698419, 2018). "Cell-type-specific TWAS using MiXcan identified five genes (ADGRV1, ZNF703, TMEM245, CDYL2, and PSG4), including three novel breast cancer susceptibility genes, that were not identified by either PrediXcan or PredictDB." (PMID 36690614, 2023).
melanoma (2 papers, 2021 to 2022). A malignant, usually aggressive tumor composed of atypical, neoplastic melanocytes. "Interestingly, among the top upregulated genes, CDYL2 was previously identified as a melanoma accelerator in a BRAFV600E model." (PMID 36202798, 2022). "Of the other six significant genes identified in the screen (TRIM28, CDYL2, DMAP1, CBX5, PYGO2), TRIM28 is known to increase melanoma tumor propagation potential." (PMID 33527896, 2021).
breast tumors (1 paper, 2020). "The analysis of publicly available databases demonstrates that CDYL2 not only is highly expressed in human testis tissues, but is also abundantly expressed in breast tumors." (PMID 32373210, 2020). "Analyses of The Clinical Proteomic Tumor Analysis Consortium (CPTAC) database 41 also revealed that the protein levels of CDYL2 were upregulated in breast tumors relative to normal breast tissues." (PMID 32373210, 2020). "Analyses of publicly available databases demonstrate that CDYL2 is abundantly expressed in breast tumors." (PMID 32373210, 2020). "Analyses of multiple publicly available databases, including ONCOMINE 38, Expression Profiling Interactive Analysis (GEPIA) 39, and The Cancer Genome Atlas (TCGA) 40, revealed that the mRNA levels of CDYL2 were significantly higher in breast tumor tissues than those in normal breast tissues." (PMID 32373210, 2020). "In contrast, CDYL2b was mainly upregulated in luminal and HER2-positive breast tumors relative to TNBC tumors, which is consistent with the expression pattern of CDYL2 in the TCGA database." (PMID 32373210, 2020).
lung carcinoma (1 paper, 2020). "Further, our combined prognosis showed that the combined high expression of SP5, FOXP1, ROBO1, DPP4, CDYL2, and STAMBPL1 is associated to patients’ better clinical prognosis of patients with lung cancer." (PMID 32552834, 2020).
nasopharyngeal carcinoma (1 paper, 2024). A carcinoma arising from the nasopharyngeal epithelium. "Initially, we scrutinized the expression of CDYL2 in gene expression profile data from clinical nasopharyngeal carcinoma tissue samples and identified no significant disparity in CDYL2 expression between nasopharyngeal carcinoma and normal nasopharyngeal epithelial tissues." (PMID 38654320, 2024). "Moreover, in nasopharyngeal carcinoma cells overexpressing or knocking down circCDYL2, RT-qPCR analysis revealed that circCDYL2 did not exert any influence on CDYL2 expression." (PMID 38654320, 2024).
cancer (5 papers, 2020 to 2024). A tumor composed of atypical neoplastic, often pleomorphic cells that invade other tissues. "CDYL2 is reported to be a binding partner of H3K9Me3 in mouse embryonic stem cells (mESCs) associated with cancer and genomic stability." (PMID 32552834, 2020). "While the role of CDYL2 in malignant tumors is scarcely documented, CDYL (chromodomain Y like), a member of the CDYL family, has been reported to govern the post-translational modification of RPA1, thereby influencing HR repair." (PMID 38654320, 2024). "CDYL2 has been identified as either a tumor suppressor or oncogene depending on the cancer type." (PMID 35176995, 2022). "However, the functional and mechanistic role for CDYL2 in human cancer remains unexplored." (PMID 32373210, 2020). "Rationale: Chromodomain Y-like 2 (CDYL2) is a member of the CDY gene family involved in spermatogenesis, but its role in human cancer has not been reported." (PMID 32373210, 2020).
infection (1 paper, 2020). The state of being infected such as from the introduction of a foreign agent such as serum, vaccine, antigenic substance or organism. "To further confirm isoform-specific functions of CDYL2, we knocked down CDYL2 in BT20 and MCF-7 cell lines, both expressing CDYL2a and CDYL2b isoforms, by lentiviral infection with expression vectors encoding shRNA targeting CDYL2 (shCDYL2) and negative control shRNA (shNC)." (PMID 32373210, 2020).
CDYL2 also shares sentences with these, for which no sentence is quoted: tumor (3 papers); colorectal cancer (2); Alport syndrome (1); myocardial infarction (1); prostate carcinoma (1).